CNDP1 (carnosine dipeptidase 1)
Diseases named in the same sentence as CNDP1 in open-access papers (continued):
Sharing a sentence is not in itself a finding about the gene and the disease.
internal carotid artery stenosis (1 paper, 2019). Carotid stenosis is a narrowing or constriction of the inner surface (lumen) of the carotid artery, usually caused by atherosclerosis. "However, these observed changes in serum CNDP1 and UCHL1 concentrations do not necessarily warrant a change in recommendations concerning the use of CEA in patients with high-grade internal carotid artery stenosis." (PMID 31460820, 2019).
leukodystrophies (1 paper, 2024). "This raises the potential for CNDP1 to serve as a generic marker of myelin insult, which includes neurodevelopmental diseases, cerebrovascular incident, and leukodystrophies." (PMID 38880880, 2024).
lung carcinoma (1 paper, 2014). "The two metabolic enzymes in the classifier, CNDP1 and CA6, are lower in the serum of lung cancer patients, perhaps in response to the low pH created by increased tumor glycolysis." (PMID 25114662, 2014).
malnutrition (1 paper, 2015). Inadequate nutrition resulting from poor diet, malabsorption, or abnormal nutrient distribution. "In both cohorts, low CNDP1 levels were associated with markers of poor prognosis including weight loss, malnutrition, lipid breakdown, low circulating albumin/IGF1 levels and poor quality of life." (PMID 25898255, 2015).
mucosal melanoma (1 paper, 2025). A melanoma that arises from a mucosal site. "For instance, in mucosal melanoma, hypomethylation-driven overexpression of CNDP1 was recently linked to a ‘cold’ TME and inferior immunotherapy outcomes." (PMID 41488620, 2025).
multiple sclerosis (1 paper, 2024). A progressive autoimmune disorder affecting the central nervous system resulting in demyelination. "Since CNDP1 is largely expressed by oligodendrocytes in the human CNS, the reduction we observe in RR patients could be due to pathological destruction of the myelin and oligodendrocytes in multiple sclerosis." (PMID 38880880, 2024).
ovarian serous cystadenocarcinoma (1 paper, 2024). A malignant serous cystic epithelial neoplasm arising from the ovary. "Conversely, we observed a negative correlation between CNDP1 expressions in KICH, LIHC, ovarian serous cystadenocarcinoma (OV), PAAD, PRAD, READ, SKCM, and UCEC with TMB." (PMID 38883336, 2024).
primary progressive MS (1 paper, 2024). "Of particular significance was the discovery that low levels of APLP1 and CNDP1, or high levels of OLFM1, may distinguish relapsing remitting MS patients from primary progressive MS." (PMID 38880880, 2024).
schizophrenia (1 paper, 2025). A major psychotic disorder characterized by abnormalities in the perception or expression of reality. "Both SERPINA5 and CNDP1 have been linked to schizophrenia as have other serine protease inhibitors." (PMID 39911945, 2025).
testicular germ cell tumor (1 paper, 2024). A germ cell tumor arising from the testis. "The findings from the EPIC algorithms revealed a significant negative association between B cell immune infiltration and CNDP1 expression in thymoma (THYM), testicular germ cell tumors, stomach adenocarcinoma (STAD), LUSC, LUAD, and HNSC." (PMID 38883336, 2024).
uterine carcinosarcoma (1 paper, 2024). A usually aggressive malignant neoplasm arising from the uterine corpus and less often the cervix. "Our findings from forest plots revealed that a low level of CNDP1 was associated with a better OS outcome specifically in uterine carcinosarcoma (UCS), KIRP, and KIRC, while high expression of CNDP1 was linked to poorer OS in THCA." (PMID 38883336, 2024).
cancer (6 papers, 2012 to 2024). A tumor composed of atypical neoplastic, often pleomorphic cells that invade other tissues. "Conversely, the expression of CNDP1 was positively correlated with macrophage, including macrophage M1 cells and macrophage M2 cells; neutrophil; endothelial cells; granulocyte–monocyte progenitor; hematopoietic stem cell; and cancer-associated fibroblast." (PMID 38883336, 2024). "Our findings indicate that the interplay between CNV, TMB, promoter methylation, and CNDP1 expression differs across cancer types." (PMID 38883336, 2024). "We then extended our research to assess the copy number variations (CNV) for the CNDP1 gene in a pan-cancer context." (PMID 38883336, 2024). "In this research, we employed CIBERSORT, EPIC, and other algorithms to explore the potential interplay between varying levels of immune cell infiltration and CNDP1 expression across diverse cancer types in the TCGA." (PMID 38883336, 2024). "We conducted an analysis to investigate the impact of CNDP1 expression on patient prognosis across various types of cancer." (PMID 38883336, 2024). "Although these studies focused on different cancer types, they all point to CNDP1 down-regulation in cancers, which are consistent with our study." (PMID 38383428, 2024). "Recent findings indicate that CNDP1 is a molecule conspicuously downregulated in various cancer forms, including HCC." (PMID 38883336, 2024). "In conclusion, our research demonstrates that CNDP1 is consistently underexpressed across various cancer types, including HCC." (PMID 38883336, 2024). "We further explored the correlation between CNDP1 expression and clinical outcomes in eight cancers, where notable differences in CNDP1 levels between cancerous tissues and their normal counterparts were observed, employing OS analysis." (PMID 38883336, 2024). "In this study, we employed the EPIC and CIBERSORT algorithms to explore the potential correlation between immune cell infiltration levels and CNDP1 expression across various cancer types in the TCGA dataset." (PMID 38883336, 2024). "In a subsequent investigation of cancer cachexia, plasma levels of CNDP1 was found to be decreased in cachexic patients, hence pointing at a metabolic role of changes in CNDP1 levels." (PMID 29507545, 2018). "We explored CNDP1 expression levels across diverse cancer types." (PMID 38883336, 2024). "Previous studies have noted certain correlations between CNDP1 and specific cancer types." (PMID 38883336, 2024). "Only through such a meticulous approach can we accurately determine whether CNDP1 presents a viable new target for cancer therapy, thus offering renewed hope to those afflicted by this disease." (PMID 38883336, 2024). "Furthermore, we investigated potential signaling pathways through which aberrant CNDP1 expression influences functional states across 33 distinct cancer types via GSEA." (PMID 38883336, 2024). "Furthermore, elevated promoter methylation levels of CNDP1 were identified in GBM compared to other cancer types." (PMID 38883336, 2024). "The mechanisms controlling the circulating levels of CNDP1 are not known and we cannot exclude that the tissue/cellular source of CNDP1 may differ between healthy subjects and cancer patients." (PMID 25898255, 2015). "It is therefore possible that reduced CNDP1 levels may be a common denominator in several more aggressive cancer forms." (PMID 25898255, 2015). "FTL is an inflammation marker also implicated in cancer, S100A9 is an important member of the Ca2+ signaling cascade reported to be altered in GBM tissue, and CNDP1 has been reported for its role in the regulation of the levels of carnosine, implicated as a potential drug for GBM." (PMID 23029420, 2012). "Survival analyses revealed that diminished expression of CNDP1 correlates with an adverse prognosis in HCC and several other types of cancer." (PMID 38883336, 2024).
cancer (continued). "Our study uncovered a total of 2,248 differentially expressed genes, with a down-regulation of CNDP1 in HCC and other cancers." (PMID 38883336, 2024). "Among the differentially expressed proteins, four factors (CNDP1, APOA4, DACH1 and BCL3) have previously been studied in different aspects of cancer, but only APOA4 and CNDP1 constitute secreted proteins." (PMID 25898255, 2015). "Consequently, in this study, we investigated the relationship between CNDP1 expression and CNV, TMB, and promoter methylation across various cancers." (PMID 38883336, 2024). "The link between CNDP1 and cancer seems not to be universally applicable, but rather appears to be contingent upon a variety of factors, including the type of tumor, its developmental stage, and individual patient variations." (PMID 38883336, 2024). "In our literature search, we found no publications that have conducted pan-cancer analyses of CNDP1 from a comprehensive tumor perspective." (PMID 38883336, 2024). "Furthermore, CNDP1 and APOA4 have been shown to be altered in plasma/serum of cancer subjects." (PMID 25898255, 2015).
tumor (6 papers, 2014 to 2025). "Carnosine is thought to have anti-tumor properties, and the plasma level of carnosine dipeptidase 1 is reduced in aggressive PCa." (PMID 41440999, 2025). "The tumor data obtained from TCGA were classified into low and high expression groups based on the level of CNDP1 expression (median)." (PMID 38883336, 2024). "AS-IV reduces cell surface PD-L1 expression through the miR-135b-5p/CNDP1 axis, enhancing anti-tumour immune responses." (PMID 37894415, 2023). "CNDP1 is involved in antigen processing and presentation in the defence system, aiding in identifying and aiming abnormal cells in the body, such as infected or tumour cells." (PMID 37894415, 2023). "We delved further into the correlation between the variation in CNDP1 expression and the prognostic outcomes in HCC patients across varying tumor microenvironments." (PMID 38883336, 2024). "Carnosinase 1(CNDP1), primarily synthesized in brain, secreted into CSF, and finally secreted into the blood, is likely to be important in the maintenance and bioavailability of carnosine, a drug for tumours." (PMID 31186631, 2019). "The proteins in our classifier are related to the biology of tumor growth and function to sustain proliferation and activate invasion (MMP7 and MMP12), and respond to oxidative stress and deregulation of cellular energetics (CNDP1 and CA6)." (PMID 25114662, 2014).
neurological disease (2 papers, 2014 to 2024). "Alteration of CNDP1 expression or activity can result in neurological disease, in part due to the dyshomeostasis of the better-studied substrate carnosine." (PMID 38880880, 2024). "Reduced activity levels of CNDP1 have been found in other neurological disorders including Parkinson’s disease, multiple sclerosis, and following a cerebrovascular event." (PMID 24566305, 2014).
psychiatric disorder (2 papers, 2020 to 2023). A disorder characterized by behavioral and/or psychological abnormalities, often accompanied by physical symptoms. "We identified shared changes in CSF levels of some proteins across two or three major psychiatric disorders including MDD, BI disorder, and SCZ (e.g., NRXN3, CNDP1, LINGO1) indicating shared neuropathology across these diseases." (PMID 32398672, 2020).
CNDP1 also shares sentences with these, for which no sentence is quoted: end-stage renal disease (2 papers); albuminuria (1); atherosclerosis (1); breast invasive carcinoma (1); carnosinemia (1); cervical squamous cell carcinoma (1); Cirrhosis (1); colon adenocarcinoma (1); diabetic retinopathy (1); endocervical adenocarcinoma (1); esophageal carcinoma (1); gestational diabetes mellitus (1); glomerulonephritis (1); heart failure (1); Hyperglycemia (1); ischemic heart disease (1); kidney transplant (1); lymph node metastasis (1); metabolic myopathy (1); metastatic prostate carcinoma (1); ovarian carcinoma (1); pancreatic adenocarcinoma (1); Parkinson disease (1); rectum adenocarcinoma (1); relapsing remitting MS (1); thymoma (1).